COL28A1 (collagen type XXVIII alpha 1 chain)
Description:
May act as a cell-binding protein.
Synonyms: COL28
Tractability: Antibody: its Gene Ontology location is reachable by antibodies, with high confidence; UniProt places it where antibodies can reach, with medium confidence; UniProt predicts a signal peptide or a membrane-spanning region. PROTAC: ubiquitination databases record sites on it. Other modalities: an approved drug acts on it.
Gene: Protein-coding gene on chromosome 7 (7,356,203 to 7,535,873, reverse strand). Ensembl gene ENSG00000215018.
Subcellular location: Secreted, extracellular space, extracellular matrix, basement membrane
Subcellular location (Human Protein Atlas): Cytosol; Nucleoplasm; Predicted to be secreted
Pathways (Reactome):
Extracellular matrix organization: Collagen biosynthesis and modifying enzymes; Collagen chain trimerization
Gene Ontology:
Molecular function: extracellular matrix structural constituent conferring tensile strength; serine-type endopeptidase inhibitor activity
Biological process: collagen fibril organization; skeletal system morphogenesis
Cellular component: extracellular matrix; collagen type XXVIII trimer; endoplasmic reticulum lumen; extracellular region; basement membrane
Genetic constraint (gnomAD): Loss-of-function variants: 69 observed, 75.02 expected, observed/expected ratio (o/e) 0.92, 90% interval 0.76 to 1.12. The upper end of that interval is the gene's LOEUF score, 1.12, which puts it in group 4 of 6, group 1 being the genes least tolerant of losing a copy. Missense variants: 858 observed, 802.76 expected, observed/expected ratio (o/e) 1.07, 90% interval 1.01 to 1.13. Synonymous variants: 300 observed, 279.09 expected, observed/expected ratio (o/e) 1.07, 90% interval 0.98 to 1.18.
Homologues: Orthologues: chimpanzee COL28A1 (99% identical), macaque COL28A1 (98% identical), dog COL28A1 (87% identical), rat Col28a1 (86% identical), guinea pig COL28A1 (86% identical), pig COL28A1 (86% identical), mouse Col28a1 (86% identical), rabbit COL28A1 (85% identical), tropical clawed frog col28a1 (52% identical). Paralogues in human: COL5A1 (31% identical), COL11A1 (31% identical), COL11A2 (29% identical), COL5A3 (29% identical), COL4A5 (29% identical), COL4A1 (29% identical), COL2A1 (28% identical), COL1A1 (27% identical), COL5A2 (27% identical), COL4A2 (27% identical), COL1A2 (27% identical), COL3A1 (26% identical), and 25 more.
Diseases named in the same sentence as COL28A1 in open-access papers:
COL28A1 is named in the same sentence as 13 diseases in open-access papers, as found by Europe PMC text mining. Sharing a sentence is not in itself a finding about the gene and the disease. The quoted sentences say what the papers report.
renal fibrosis (2 papers, 2022 to 2023). A final common manifestation of a wide variety of chronic kidney diseases characterized by glomerulosclerosis and tubulointerstitial fibrosis. "Besides its role in various diseases, COL28 is expressed in the kidney, and COL28A1 polymorphisms appear to modulate the development of diabetic nephropathy, a disease involving renal fibrosis." (PMID 36883360, 2023).
Cirrhosis (1 paper, 2015). A chronic disorder of the liver in which liver tissue becomes scarred and is partially replaced by regenerative nodules and fibrotic tissue resulting in loss of liver function. "Patients with cirrhosis showed increased expression in blood of eight genes coding for collagen synthesis COL4A6, COL5A1, COL11A2, COL12A1, COL27A1, COL28A1, COL23A1, COL14A1." (PMID 26317806, 2015).
virus infection (1 paper, 2014). "Interestingly, Col28a1 contains a serine protease inhibitor domain, which could be important in reducing inflammation or virus infection." (PMID 25418976, 2014).
tumor (7 papers, 2018 to 2025). "Wnt/β-catenin signaling activates CTNNB1 (β-catenin) through WNT1, promoting the expression of collagen (such as COL1A1 and COL28A1), thereby increasing the adhesion and matrix invasion ability of tumor cells." (PMID 40989695, 2025). "In detail, tumor cells upregulated COL20A1, COL28A1 and TGFB1 expression to recruit more myofibroblasts in TTs compared with in PTs." (PMID 35361264, 2022).
cancer (4 papers, 2022 to 2024). A tumor composed of atypical neoplastic, often pleomorphic cells that invade other tissues. "The highest expression of genes encoding Col1a1-2, Col3a1, Col4a1, Col4a2, Col5a1, Col5a2, Col6a1, Col8a1, Col9a3, Col10a1, Col12a1, Col14a1, Col15a1, Col16a1, Col18a1, and Col28a1 were detected in untreated tumors, whose landscapes were dominated by Krt8+ cancer cells." (PMID 39372930, 2024).
COL28A1 also shares sentences with these, for which no sentence is quoted: glioblastoma (2 papers); lung fibrosis (2); diabetic nephropathy (1); heart failure (1); infection (1); kidney diseases (1); lung carcinoma (1); Ureteral obstruction (1).